IL1A (interleukin 1 alpha)
Diseases named in the same sentence as IL1A in open-access papers (continued):
Sharing a sentence is not in itself a finding about the gene and the disease.
tumor (continued). "For example, HER2-overexpressing BCa cells show IL-1α-dependent tumor growth and lung metastasis in vivo." (PMID 35626710, 2022). "A comparison of chemical-induced tumor incidence in mice lacking expression of IL-1RI ligands revealed that IL-1Ra expression strongly protects from tumors, IL-1α had a weak protective effect, whereas IL-1β strongly supports tumor development." (PMID 36293159, 2022). "Mutant BRAF suppresses intratumoral T cells via overexpression of IL-1α and IL-1β by tumor cells, leading to overexpression of PD-L1 and PD-L2 in tumor-associated fibroblasts." (PMID 35703181, 2022). "The pro-tumor and pro-metastasis effects of IL-1α have been well described in different malignancies, see recent review." (PMID 36426368, 2022). "In contrast to the role of secreted IL‐1α, intracellular and membrane‐bound IL‐1α activates immune mechanisms that lead to tumour destruction." (PMID 35344301, 2022). "The most protruding TME member in these cells is the tumor-associated macrophages (TAMs), which mediate tumor proliferation by secreting growth factors and inflammatory mediators such as CCL2, IL-1α, IL-6 and TNF-α and induce treatment resistance in cancer." (PMID 35736173, 2022). "Another possibility is that IL-1α acts on OPCs and independently alters the signaling pathways of tumor-induced and RANKL-induced osteoclastogenesis." (PMID 36614130, 2022). "The Apte lab systematically studied the role of IL-1α or IL-1β in tumor initiation and progression using several genetically engineered mouse models." (PMID 36074553, 2022). "The high expression of IL-1α has been regarded as a tumor aggressiveness promoter leading to poor survival of HNSCC patients." (PMID 35875097, 2022). "As detected in tumor-induced osteoclastogenesis, IL-1α significantly stimulated RANKL-induced osteoclastogenesis." (PMID 36614130, 2022). "For instance, IL-1α produced by necrotic tumor cells can directly stimulate the proliferation of neighboring cells and promote tumor progression." (PMID 35237304, 2022). "Of note, none of the OPC patients’ plasma contained measurable levels of IL-1α, suggesting that monocyte exposure to IL-1α occurs locally via passage through the tumor or is delivered to blood monocytes by a different mechanism." (PMID 36426368, 2022). "Given that IL-1A has both pro- and anti-tumor effects, its role in cancer development is controversial." (PMID 36071472, 2022). "IL-1α and IL-1β can stimulate tumor growth and metastasis via upregulating the expression of angiogenic factors such as IL-8 and vascular endothelial growth factor (VEGF)." (PMID 35399416, 2022). "IHC of 136 primary BCa tumor tissues performed by Liu and colleagues revealed that elevated IL-1α protein levels positively correlate with HER2+ status." (PMID 35626710, 2022). "In vitro studies of bladder cancer cell lines revealed a high content of interleukin (IL)-1α in tumour conditioned media (CM)." (PMID 36313650, 2022). "Experiments based on chemically induced skin carcinogenesis revealed an important role for IL-1α derived from keratinocytes/tumor cells." (PMID 36293159, 2022). "Although none of these selected factors, alone or in combination, induced osteoclasts from OPCs, IL-1α and IL-1β stimulated tumor-induced and RANKL-induced osteoclastogenesis." (PMID 36614130, 2022). "Among the key cytokines, TGF‐β and IL1α influence fibroblast phenotypes in opposing ways to polarise and generate the myCAF and iCAF populations in multiple tumour types." (PMID 35533046, 2022). "Among the candidate factors, IL-1α and IL-1β were suggested to have osteoclastogenic activity and were thought to be strong participants in tumor-induced osteoclastogenesis." (PMID 36614130, 2022). "IL-10 can also induce tumor progression by inhibiting many cytokines such as IL-1a, IL-1b, IL-6, IL-8, IL-12, and IL-18." (PMID 35186043, 2022).
tumor (continued). "Proinflammatory cytokines produced by the tumor, such as IL-1a, IL-1b, IL-6, and TNF-α, can cross the blood–brain barrier (BBB) and migrate to the brain." (PMID 35736871, 2022). "A number of studies have shown the pleiotropic roles that IL-1α plays in immune regulation in the tumor milieu surrounding OSCCs." (PMID 35740551, 2022). "Meanwhile, IL-1A and IL-6 of Puget grade 2 tumor invasion to the hypothalamus were identified using LASSO regression." (PMID 36389809, 2022). "In support of these findings, other studies showed that IL-1α or IL-1β levels are inversely correlated with ERα and/or PR levels in BCa tumor tissue from primary or regional metastasis." (PMID 35626710, 2022). "IL-1α/β have also long been considered as crucial cytokines in cancer, however often contradictory pro- or anti-tumorigenic roles were found in different tumor models or clinical studies." (PMID 36074553, 2022). "As to the pro-tumor ability, both IL-1β and IL-1α are found to contribute to tumor angiogenesis and invasiveness in the process of PCa progression." (PMID 36237303, 2022). "Recently, breast tumor-derived IL-1α was reported to act on tumor-infiltrating myeloid cells inducing the expression of thymic stromal lymphopoietin (TSLP), a factor that was crucial for tumor survival and metastatic spreading." (PMID 35743911, 2022). "Both IL-1α and IL-1β were shown to exert a dual functions in promoting and suppressing tumor progression." (PMID 36237303, 2022). "On the contrary, other experimental data have reported a tumor promoting effect for IL-1α in pancreatic cancer by maintaining a pro-tumor inflammatory microenvironment through stimulation of cancer associated fibroblasts (CAFs)." (PMID 35743911, 2022). "IL-1 (including both IL-1α and IL1-β) and IL-6 stimulate RANKL-induced osteoclastogenesis under inflammatory conditions, but they are also associated with tumor-induced osteoclastogenesis in vitro and in vivo." (PMID 36614130, 2022). "Tissue damage occurring during tumor development and the release of alarm cytokines such as IL-1α, IL-1β, and TNFα induce the production of IL-6, IL-10, IL-11, and IL-23 by tissues and myeloid cells." (PMID 33498483, 2021). "In the tumour stroma‐derived EVs, enrichment of IL1A, IL1B, and SNAI1 was consistent with a more inflammatory stromal phenotype typically associated with disease." (PMID 34596356, 2021). "We observed higher expression of Arg1, Il1a, and Rgs1 in macrophages from scaffolds compared with those from the primary tumor." (PMID 33782087, 2021). "Several studies have demonstrated that IL1α and IL1β are overexpressed in various tumours including endometrial cancer, and promote cell proliferation, adhesion, invasion, and angiogenesis." (PMID 34357126, 2021). "OSCC cells produce IL-1α, which induces the proliferation and cytokine secretion by cancer-associated fibroblasts (CAFs) (CCL7, CXCL1, and IL-8), promoting tumor progression." (PMID 35047997, 2021). "The authors also found that IL-1α played an important role in controlling immune-surveillance of the developing tumor." (PMID 33430381, 2021). "IL-1α expression is also reported to be increased in the saliva of tongue SCC (TSCC) patients compared to controls and has also been associated with tumor growth pattern." (PMID 35048046, 2021). "MDSCs can directly promote tumor progression by affecting TME remodelling and angiogenesis via soluble factors like VEGF and can inhibit tumor cell senescence by antagonizing IL-1α." (PMID 34768810, 2021). "In the mice models, membrane IL-1α was able to activate anti-tumor immunity via promoting CD8+ T- and NK-cells functions against the malignant cells." (PMID 33430381, 2021). "Similar to other tumors, the constitutive activation of NF-κB in PDAC is primarily determined by pro-inflammatory cytokines, such as TNF and IL-1α released by tumor-infiltrating immune cells." (PMID 34572737, 2021).
tumor (continued). "In line with the observed changes in the heart and the liver, tumor-bearing mice had significantly increased renal expression of the pro-inflammatory cytokines IL-1α, IL-1β, TNF-α, and Mcp-1 compared to tumor-free mice." (PMID 34445729, 2021). "To further confirm the effect of hypoxia on the cytokine expression of macrophages co-cultured with tumor cells, we knocked down the hypoxia modulator, HIF1α, in A549 cells and analyzed the expression of IL1A and IL6." (PMID 34362882, 2021). "Cytokine profiling on tumor protein extracts showed a substantial increase in the expression of IL-1α and β, CXCL9 and CXCL10 in pre-terminal gal-9-KO tumors by comparison with WT and aggressive gal-9-KO tumors." (PMID 33664349, 2021). "IL-1α expression also correlated with increased cell transmigration of tumor cells across the endothelium, which was inhibited by addition of IL-1RA." (PMID 35048046, 2021). "In another study, a team confirmed that IL-1α and β are essential for a complete Th1- induced anti-tumor response in melanoma." (PMID 33498483, 2021). "In an oncogene-transformed NIH/3Y3-derived cell line overexpressing cytosolic or membrane-bound forms of IL-1α, IL-1α exerts adjuvant-like effects, increasing the immunogenicity of tumor-cell antigens and regression of the tumor." (PMID 33430381, 2021). "Our data suggested that the changes in miR101 in the tumor-derived exosomes played an important role in IL1A and IL6 expression in macrophages, although the hypoxic stress did not change the total amount of exosome secretion." (PMID 34362882, 2021). "Other cytokines that consistently showed significant inhibition by muscle‐specific SIRT6 over‐expression in tumour settings were IL‐1α and IL‐16." (PMID 34212132, 2021). "Another group investigated the mechanism of this tumor suppressive effect and found that the IL-1α activated the development of tumor cell-specific cytotoxic T lymphocytes (CTL)." (PMID 33430381, 2021). "TNF-α and IL-1α in tumor microenvironment can produce DNA damage molecules such as ROS and nitric oxide, which induce mutations in colonic epithelium and promote the development of cancer." (PMID 34930323, 2021). "The roles of IL1α in cancer biology are various, with either a pro‐tumorigenic role or tumor suppressor." (PMID 33931964, 2021). "This is probably achieved by the capability of IL-1α to induce transmigration of tumor cells across the endothelium and to enhance the expression of metastatic genes, such as MMP-9, PGE2, VEGF, and IL-8." (PMID 35047997, 2021). "IL-1α and IL-1β in the tumor microenvironment play critical roles in colorectal cancer growth by inducing tumor-elicited inflammation through IL-17A and IL-22 production in T cells." (PMID 33406733, 2021). "IL-1α is constitutively secreted and has been reported to possess tumor-promoting or tumor-suppressing properties depending on the type of malignancy." (PMID 34842843, 2021). "IL1A is one of the prominent inflammatory cytokines and contributes to tumor invasion, angiogenesis, and metastasis by inducing VEGF, TNF-α, HGF, and TGF-β." (PMID 34203721, 2021). "The five-year distant metastasis-free survival was 70% for patients with high tumor levels of IL-1α in contrast to 95% for patients with low expression of IL-1α." (PMID 35048046, 2021). "Here, we summarized the recent progress for the role of IL-1α in multiple cancer types and the possible mechanisms of how IL-1α promoted or inhibited tumor growth." (PMID 33430381, 2021). "Other authors have reported that tumor cell-derived IL1α induces HGF secretion by CAFs, enhancing in turn the metastatic potential of tumor cells." (PMID 34066976, 2021). "IL-1α’s action is mainly immunostimulatory, while IL-1β exhibits a pro-inflammatory role, especially in the early phases of tumor development." (PMID 33557173, 2021). "The release of IL-1α resulted in the recruitment of inflammatory cells that accelerated the progression to gastric pre-neoplasia." (PMID 33430381, 2021).
tumor (continued). "IL-1α, IL-1β, and IL-1R which are commonly expressed by tumor-infiltrating immune effector cells and tumor stromal cells are responsible for shaping the tumor microenvironment." (PMID 34220337, 2021). "ICAFs are driven by tumor secretory factors, such as Interleukin-1 alpha (IL-1α) and Interleukin 1 beta (IL-1β), and gather at the edge of the tumor." (PMID 34067040, 2021). "In endometrial cells, these two bacteria can also induce the production of IL-1α, IL-1β, IL-17α, and TNFα, pro-inflammatory cytokines which are involved in the carcinogenesis of various tumours." (PMID 34357126, 2021). "This study proposes a new mechanism, whereby hypoxia elicits inflammation in the tumor microenvironment by inhibiting exosomal miR101, which stimulates IL1A and IL6 expression in macrophages, leading to inflammation." (PMID 34362882, 2021). "As an important pro-inflammatory cytokine, the role of IL-1α in cancer growth has been studied in various cancer types, and the results suggested IL-1α is a dual function cytokine which exerts pro- and anti-tumor function in different cancers." (PMID 33430381, 2021). "We previously reported that in tumor cells, mutation of both NLS and calpain cleavage site led to increased membrane localization of pro-IL-1α, suggesting the NLS signal and protease cleavage reduced pro-IL-1α membrane translocation." (PMID 33430381, 2021). "Tumor-bearing mice had significantly elevated hepatic expression of the pro-inflammatory cytokines IL-1α, IL-1β, TNF-α, Cxcl9, and Cxcl10 compared to tumor-free mice." (PMID 34445729, 2021). "Hypoxia stress reduced the secretion of exosomal miR101 from tumor cells, which led to the induction of IL1A and IL6 in macrophages, in turn promoting lung tumor cell growth." (PMID 34362882, 2021). "The role of IL-1α in cancer development is controversial as it exerts both pro- and anti-tumor roles in different cancer types." (PMID 33430381, 2021). "In HER2+ BC, HER2 induced expression of IL-1α and IL-6, which then increased drug-resistance-related CSCs in primary tumor, while blocking IL-1 signaling increased the efficacy of chemotherapy when combined with cisplatin and paclitaxel." (PMID 34602858, 2021). "Meanwhile, another study looking at the function of the membrane IL-1α in murine HCC models found potential inhibitory functions on tumor development via immune cell activation." (PMID 33430381, 2021). "IL-1α can be localized in the nucleus, where it acts as a transcription factor to regulate cell differentiation in normal cells, as well as neoplasia in cancer cells." (PMID 32635472, 2020). "In one study, TSLP produced by myeloid cells after activation with tumor cell-derived IL-1α activated anti-apoptotic pathways in TSLPR-expressing tumor cells, through Bcl-2." (PMID 33042121, 2020). "Meanwhile, the levels of proinflammatory cytokines (tumor necrosis factor (TNF)-α, interleukin (IL)-β, IL-1α, and IL-6) were also increased, indicating the formation of a beneficial inflamed tumor microenvironment." (PMID 32111828, 2020). "Conversely, the mRNA expression of S100A14, IL1A, CCL2, CXCL3 and CXCL5 in tumor tissues derived from S100A14-deficient mice was significantly reduced compared with those from their WT counterparts." (PMID 32483412, 2020). "Further experiments suggested the IL-1α/IL-1R/MYD88/IL-6 pathway as responsible for the reduced anti-tumor efficacy of erlotinib and other EGFR inhibitors." (PMID 33115415, 2020). "Both cell lines secreted Gm-csf, Tnf-α, Ccl-2, Ifn-γ, and IL-1α while Timp1 was uniquely secreted by the PyMT+ tumor line." (PMID 31941005, 2020). "We next investigated if tumor-secreted BMP7 regulates IL1A, IL1B, TNF, and CCL5 via MAPK14 in macrophages." (PMID 32973129, 2020). "Overexpression of the IL-1 agonists IL-1a and IL-1b has been shown to promote tumor invasiveness and metastasis by inducing the expression of angiogenic genes and growth factors." (PMID 32894202, 2020).
tumor (continued). "IL1α secreted from tumor cells can promote tumorigenesis in an autocrine manner, and stimulate fibroblasts in a paracrine fashion." (PMID 33105540, 2020). "In a study on Ni-refinery workers, IL1A, a cytokine known to be elevated in many tumor types, was the most upregulated gene in the blood cells." (PMID 32244462, 2020). "Pro-inflammatory cytokines, including TNF-α, IL-1α, IL-1β, and IL-6, in the tumor microenvironment have been reported to promote tumor progression, metastasis, and invasion." (PMID 33348858, 2020). "One expected outcome of p63-mediated IL1A hyperactivation would be a strengthened concentration gradient of IL-1α emanating from tumor cells to promote iCAF induction within the stroma." (PMID 32329713, 2020). "Firstly, levels of several pro‐inflammatory mediators (e.g. MCP‐1, IL‐1α, intermediate monocytes) inversely correlated with different tumor immune infiltrate markers." (PMID 33024560, 2020). "Currently, accumulating studies have demonstrated that chronic inflammation related to cellular senescence plays a key role in tumor immunosuppression and major proinflammatory factors, including IL-1α, IL-1β, IL-6 and IL-8." (PMID 33232279, 2020). "Based on the results from proteome profiler, NLC-Citral reduced the level of IL-6 and IL-1α expression in the 4T1 tumor." (PMID 32526880, 2020). "This association of CCF‐activated STING with inflammatory gene expression (IL‐1A/B, IL‐6, IL‐8) was supported by clinical tumor expression data." (PMID 32918364, 2020). "In melanoma cells, both IL-1α and IL-1β can promote tumor angiogenesis by activating NF-κB signaling pathways to induce the expression of IL-6, IL-8, intercellular adhesion molecule-1, and tissue factor." (PMID 32993787, 2020). "Notable downregulation of growth factors (VEGFD, FGF2, PGF, TNF-α) and cytokine IL-1A was observed in tumor cells upon treatment with 5a." (PMID 31842391, 2019). "We next investigated if systemic i.p. delivery of recombinant IL-1α (rIL-1α) would enhance tumor response to cetuximab." (PMID 30890189, 2019). "We summarize here that in immunocompetent mice, IL-1α as a single agent and in combination with cetuximab demonstrates anti-tumor activity and that gender differences influence drug response in this mouse model." (PMID 30890189, 2019). "Cancer cells, tumor-infiltrating immune effector cells, and tumor stromal cells express IL-1α, IL-1β, and IL-1R." (PMID 31557902, 2019). "The flavonoids of Hippophaerhamnoides L (TFH) isolated from berries of sea buckthorn up-regulated the levels of IL-1α, IL-2, IL-7, IL-15 etc. to activate NK cells and its cytotoxicity against tumor cells K562." (PMID 31138762, 2019). "Despite these previous observations, little is known about the in situ tumor expression of IL-1α in HNSCCs, the subcellular distribution of IL-1α in HNSCC tumors, and the prognostic significance of IL-1α localization in HNSCC patients." (PMID 31320902, 2019). "Both CD4+ and CD8+ T cell depletion significantly reversed the anti-tumor effect of CTX + IL-1α-NP, and CD8+ T cell depletion was significantly more effective than CD4+ T cell depletion at reversing the anti-tumor effect of CTX + IL-1α-NP." (PMID 30890189, 2019). "IL‐1α and IL‐1β bind to the same receptor and perform similar biological activities, such as promoting tumor growth and metastasis via enhanced angiogenesis." (PMID 31102307, 2019). "Others have delved further into the mechanism investigating how IL-1α is activated in cancer cells and how this effects neovascularisation and subsequent tumor growth." (PMID 31293586, 2019). "Inhibition of IL-1α alone reduced the crosstalk-induced production of these inflammatory factors, indicating a key role for IL-1α in the formation and maintenance of the inflammatory tumor environment." (PMID 31231372, 2019). "These authors demonstrate that HER2 expression in the tumor drives a positive feed-forward activation loop, inducing the expression of IL-1α and IL-6." (PMID 31231372, 2019).